Y_RNA (Y RNA )
Gene: Miscellaneous RNA gene on chromosome 22 (31,230,071 to 31,230,172, reverse strand). Ensembl gene ENSG00000202019.
Homologues: Orthologues: chimpanzee Y_RNA (100% identical), macaque Y_RNA (92% identical). Paralogues in human: Y_RNA (87% identical), Y_RNA (86% identical), RNY3 (85% identical), Y_RNA (85% identical), RNY3P13 (84% identical), Y_RNA (84% identical), Y_RNA (83% identical), RNY3P1 (82% identical), RNY3P16 (82% identical), RNY3P2 (82% identical), Y_RNA (82% identical), Y_RNA (81% identical), and 96 more.